SIRT1 (sirtuin 1)
Diseases named in the same sentence as SIRT1 in open-access papers (continued):
Sharing a sentence is not in itself a finding about the gene and the disease.
dysferlinopathy (1 paper, 2019). "Because phenotypes of SIRT1-MKO mice were similar to those of dysferlinopathy (see Discussion), we examined whether membrane resealing in C2C12 myoblast cells was affected by SIRT1 inhibition." (PMID 31242212, 2019). "In the present study, we showed that SIRT1-MKO mice had pathological and physiological characteristics similar to those of mild dystrophies, especially dysferlinopathy." (PMID 31242212, 2019).
embryonic carcinoma (1 paper, 2021). "Knockdown of SIRT1 fostered neurogenesis of P19 embryonic carcinoma cells." (PMID 34650436, 2021).
endometrial tumor (1 paper, 2021). "This demonstrated that SIRT1 may play a role as a tumor promoter in EC and can promote endometrial tumor growth by promoting lipogenesis, which is why SIRT1 may be regarded as the target of the management of EC." (PMID 33435147, 2021).
enteropathy (1 paper, 2023). "Using mouse and organoid models of malnutrition induced enteropathy, we discovered that low plasma tryptophan was associated with a reduction in SIRT1 mediated mitochondrial biogenesis and autophagy activity." (PMID 37738832, 2023). "This study aimed to reveal whether the tryptophan-NAD+-SIRT1 and autophagy pathways are involved in the aetiology of SM-induced enteropathy and whether modulating these pathways can protect intestinal structure and function." (PMID 37738832, 2023).
enterovirus infection (1 paper, 2023). "This suggests a non-deacetylase role of SIRT-1 in ER stress, at least during enterovirus infection." (PMID 37850626, 2023).
ER stress (1 paper, 2020). "Therefore, SIRT1 activation, by enhancing protective autophagy and reducing detrimental apoptosis, could constitute a promising therapeutic strategy to limit the development and progression of cardiac diseases associated with ER stress." (PMID 32059483, 2020).
erectile dysfunction (1 paper, 2025). Persistent or recurrent inability to achieve or to maintain an erection during sexual activity. "Furthermore, the inhibition of SIRT1 expression in CCSMCs has been associated with erectile dysfunction." (PMID 39871297, 2025).
Erythrocytosis (1 paper, 2022). "Erythrocytosis is only one of the downstream effects from SIRT1 activation." (PMID 35658864, 2022).
Fanconi anemia (1 paper, 2022). Fanconi anemia (FA) is a hereditary DNA repair disorder characterized by progressive pancytopenia with bone marrow failure, variable congenital malformations and predisposition to develop hematological or solid tumors. "The therapeutic value of resveratrol and another Sirt1 activator SRT3025 in Fanconi anemia has been established at the rodent animal level." (PMID 35342358, 2022).
Follicular Cyst (1 paper, 2024). Cyst due to the occlusion of the duct of a follicle or small gland. "In conclusion, the data demonstrate that quercetin can inhibit oxidative stress and apoptosis in the follicles of cows with follicular cysts, and that these effects are related to the level of autophagy regulated by the SIRT1/ROS/AMPK signaling pathway." (PMID 39232832, 2024).
follicular lymphoma (1 paper, 2022). Follicular lymphoma is a form of non-Hodgkin lymphoma characterized by a proliferation of B cells whose nodular structure of follicular architecture is preserved. "SIRT levels have also been explored in follicular lymphomas (FL) compared to DLBCL and follicular hyperplasia, indicating that in FL, SIRT1 was more expressed compared to follicular hyperplasia and DLBCL." (PMID 36230534, 2022).
Friedreich ataxia (1 paper, 2015). An inherited condition that affects the nervous system and causes movement problems. "It is of interest that Vitamin B3 (nicotinamide), an inhibitor of SIRT1, has shown promise in Phase I trials for Friedreich ataxia." (PMID 26089834, 2015).
Fulminant hepatitis (1 paper, 2016). Acute hepatitis complicated by acute liver failure with hepatic encephalopathy occurring less than 8 weeks after the onset of jaundice. "So we conditionally inactivate Sirt1 in murine hepatocytes to determine its role in d-galactosamine (GalN)/lipopolysaccharide (LPS)-induced liver damage, which is a well-established experimental model mimicking septic liver injury and fulminant hepatitis." (PMID 27711079, 2016). "In the present study, we generate hepatocyte-specific Sirt1 knockout mice to explore the role of Sirt1 in d-galactosamine (GalN)/lipopolysaccharide (LPS)-induced liver damage, which is a well-established experimental model mimicking septic liver injury and fulminant hepatitis." (PMID 27711079, 2016).
glutamine metabolism disorder (1 paper, 2020). "Given the negative regulation of SIRT4 on SIRT1 and the intricate relationship between AMPK and SIRT1, we hypothesized that glutamine metabolism disorder might be involved in SIRT4-induced SIRT1 inhibition." (PMID 32863939, 2020).
granulosa cell tumor (1 paper, 2021). A slow-growing, malignant tumor, characterize by the presence of granulosa-like cells and Call-Exner bodies, that is almost always found in the ovary. "In the human ovary, granulosa cells express sirtuin 1 (SIRT1), which has also been detected in human tumors derived from granulosa cells, i.e., granulosa cell tumors (GCTs), and in KGN cells." (PMID 33669567, 2021).
growth deficiency (1 paper, 2024). "Our study shows significant inverse relationships between the SIRT1 concentration and the IGF-1 levels, the IGF-1/IGFBP-3 molar ratio and the degree of growth deficiency." (PMID 39062007, 2024).
hemangiosarcoma (1 paper, 2021). "For instance, Tenovin-6 impaired cellular growth of canine hemangiosarcoma cells through a SIRT1-independent mechanism." (PMID 34650436, 2021).
hepatic neoplasm (1 paper, 2017). "Age-dependent increase of spontaneous liver neoplasms might result from aging-induced down-regulation of SIRT1 and DLC1." (PMID 28903430, 2017).
Hepatitis C infection (1 paper, 2015). "We hypothesize that SIRT1 may contribute to the defense mechanism by modifying the acetylation and activity of SART1 during Hepatitis C infection." (PMID 26468954, 2015).
Hernia (1 paper, 2019). "The variant of rs932658 reportedly alters the transcriptional activities of the SIRT1 gene promoter and changes SIRT1 levels, contributing to hernia development." (PMID 30714469, 2019).
Hutchinson-Gilford progeria (1 paper, 2019). "The phytoalexin resveratrol is a purported activator of SIRT1 and may also enhance the binding of SIRT1 to its activator lamin A, a protein closely tied to lifespan regulation since a splice site LMNA mutation results in Hutchinson-Gilford progeria." (PMID 30666570, 2019).
Hydrocephalus (1 paper, 2025). Hydrocephalus is an active distension of the ventricular system of the brain resulting from inadequate passage of CSF from its point of production within the cerebral ventricles to its point of absorption into the systemic circulation. "Collectively, niacin regulates microglial function via the HCAR2/SIRT1/Nrf2 signaling axis to reduce neuronal damage, neuroinflammation, and oxidative stress, thereby alleviating hydrocephalus and improving neurological outcomes." (PMID 41205412, 2025).
hyper-keratosis (1 paper, 2020). "To prove this, we assessed the impact of SIRT1 silencing on sorafenib-induced hyper-keratosis." (PMID 32296111, 2020). "Taken together, all these results confirmed that JNK2, upon being phosphorylated by s-HBEGF-activated EGFR, could stabilize SIRT1 and give rise to hyper-keratosis." (PMID 32296111, 2020). "Based on these findings, we hypothesized that SIRT1, when stabilized by p-JNK2, gives rise to hyper-keratosis." (PMID 32296111, 2020).
Hyperammonemia (1 paper, 2024). An increased concentration of ammonia in the blood. "Herbacetin preserved liver function and guarded against hyperammonemia-induced neurodegenerative effects, in part via activating SIRT1/AMPK signaling, to successfully mitigate the degenerative effects that accompanied TAA-induced HE." (PMID 38762495, 2024).
hypertensive retinopathy (1 paper, 2024). Retinopathy due to hypertension. "Our research revealed that Ang II infusion may increase the expression of NLRP3 and reduce the level of SIRT1; these findings showed that Ang II-induced hypertensive retinopathy and dysfunction may involve both SIRT1 and NLRP3." (PMID 38360728, 2024). "SIRT1 adversely regulates the NLRP3 inflammasome pathway, which in turn increases Ang II-induced inflammation and hypertensive retinopathy." (PMID 38360728, 2024).
hypertrophic cardiomyopathy (1 paper, 2022). A condition in which the myocardium is hypertrophied without an obvious cause. "Yet, SIRT1’s cardioprotective effect was observed only at low dosage whereas overexpression of SIRT1 in mouse hearts was shown to produce hypertrophic cardiomyopathy." (PMID 35360010, 2022).
hypopharyngeal squamous cell carcinomas (1 paper, 2013). "It is necessary to investigate the expression of SIRT1 and DBC1 in laryngeal and hypopharyngeal squamous cell carcinomas (LSCC and HSCC) and its correlation with available clinical parameters." (PMID 23805287, 2013).
hypoxic-ischemic encephalopathy (1 paper, 2022). "Therefore, this study explored the role of CGA in HI-induced neonatal hypoxic-ischemic encephalopathy and elucidated whether the SIRT1/Nrf2/HO-1 pathway mediates this process." (PMID 35689269, 2022).
idiopathic scoliosis (1 paper, 2011). A scoliosis with no known cause. "In contrast, in idiopathic scoliosis samples this anti-proliferation activity was reversed, with SIRT1 treatment significantly upregulating the normalized proliferation activity (vs. control as percentage of control: 10 μM, +37.5% (P < 0.05) and 100 μM, +60.6% (P < 0.01))." (PMID 22152608, 2011). "In patients with idiopathic scoliosis, LDH and LSS, immunohistochemical staining confirmed SIRT1 expression and nuclear localization with β-actin localized in the cytoplasm." (PMID 22152608, 2011). "In addition, proliferation activity was upregulated by SIRT1 treatment in idiopathic scoliosis samples with relatively nondegenerated tissues, and was downregulated in LDH and LSS samples with more degenerated IVD tissues." (PMID 22152608, 2011).
infectious colitis (1 paper, 2023). A viral or bacterial infectious process affecting the large intestine. "Building on our previous study, we show here that both the transcript and protein levels of SIRT1 are decreased in murine models of chemically induced and infectious colitis." (PMID 37744380, 2023). "To determine if NR treatment had similar effects on the SIRT1-PGC1α axis during infectious colitis, we assessed the SIRT1-PGC1α axis in mice infected with C. rodentium and treated with NR or Vehicle." (PMID 37744380, 2023).
inflammatory skin disease (1 paper, 2011). Inflammatory skin disorders covers a broad category that includes many conditions ranging in severity, from mild itching to grave medical health complications These disorders are common in people of all ages and races. "To evaluate whether Sirt1 could represent a possible therapeutic target for the treatment of inflammatory skin diseases characterized by a prominent microvessel involvement, we analyzed Sirt1 expression in vivo in the microvessels of normal and psoriatic skin." (PMID 21931678, 2011).
Inguinal hernia (1 paper, 2019). Protrusion of the contents of the abdominal cavity through the inguinal canal. "Genetic studies from China revealed that DNA sequence variants (DSVs) might contribute to inguinal hernia development by changing the transcriptional activities of TBX1, TBX2, TBX3, Sirtuin 1, and GATA transcription factor 6 (GATA6) gene promoters." (PMID 31024927, 2019).
insomnia (1 paper, 2025). A sleep disorder characterized by difficulty in falling asleep and/or remaining asleep. "Additionally, resveratrol's treatment of insomnia is closely linked to the SIRT1, AMPK, NF-κB, mTOR, PI3K/Akt, and MAPK pathways." (PMID 40144750, 2025). "Insomnia patients usually exhibit circadian rhythm disorders, and resveratrol can regulate the expression of biological clock genes BMAL1 and PER2 by activating SIRT1, thus adjusting the sleep–wake cycle and improving sleep quality." (PMID 40144750, 2025).
interstitial lung disease (1 paper, 2022). A diverse group of lung diseases that affect the lung parenchyma. "In SSc, the reduction in circulating SIRT1 and SIRT3 associated with a greater extent of cutaneous fibrosis, presence of interstitial lung disease, and worse pulmonary function." (PMID 35268452, 2022).
intraepithelial neoplasia (1 paper, 2012). A precancerous neoplastic process that affects the squamous, glandular, or transitional cell epithelium without evidence of invasion. "In this group only a subset of mostly high grade intraepithelial neoplasia and carcinoma was characterized by elevated c-MYC and SIRT1 expression." (PMID 23045412, 2012). "In lesions with high grade intraepithelial neoplasia, c-MYC expression was found at a moderate to high level, whereas SIRT1 expression was restricted to single cells." (PMID 23045412, 2012). "In lesions with low grade intraepithelial neoplasia, c-MYC was expressed at low level with very few weakly positive SIRT1 expressing cells distributed throughout the lesions." (PMID 23045412, 2012). "For instance in some lesions with high grade intraepithelial neoplasia and KRAS mutation that displayed high c-MYC and SIRT1 expression, no nuclear beta-catenin was detected, whereas other lesions with equally high c-MYC and SIRT1 levels were positive for nuclear beta-catenin (data not shown)." (PMID 23045412, 2012).
intrahepatic cholangiocarcinoma (1 paper, 2025). A carcinoma that arises from the intrahepatic bile duct epithelium in any site of the intrahepatic biliary tree. "In intrahepatic cholangiocarcinoma (ICC), hepatocyte-secreted CCL3 promotes metastasis via VIRMA-mediated m6A modification, which upregulates SIRT1 and drives tumor progression." (PMID 40034695, 2025).
invasive carcinoma (1 paper, 2012). A carcinoma that is not confined to the epithelium, and has spread to the surrounding stroma. "In lesions and invasive carcinomas of the serrated route, high c-MYC and SIRT1 levels were associated with K-Ras, B-Raf, or in a minor fraction, with Wnt pathway activation." (PMID 23045412, 2012). "Hence, unscheduled c-MYC expression together with elevated SIRT1 activity in serrated lesions and invasive carcinomas may repress the two major tumor suppressive mechanisms, apoptosis and senescence and thus support cell survival, expansion and cancer progression." (PMID 23045412, 2012). "In invasive carcinomas, we identified two groups with respect to the c-MYC and SIRT1 levels: One group comprised four cases (45%) which displayed negative to low c-MYC expression and negative SIRT1 staining." (PMID 23045412, 2012).
Kaposi's sarcoma (1 paper, 2022). A malignant neoplasm characterized by a vascular proliferation which usually contains blunt endothelial cells. "Conversely, Sirt1 knockdown promoted Kaposi’s sarcoma-associated herpesvirus replication." (PMID 35693834, 2022).
keratosis (1 paper, 2020). A skin disorder consisting of hypertrophy of the stratum corneum of the skin. "Activated JNK2 then stabilizes SIRT1, ultimately leading to hyper-keratosis, a characteristic feature of HFSR." (PMID 32296111, 2020).
kidney cancer (1 paper, 2024). Primary or metastatic malignant neoplasm involving the kidney. "Furthermore, we validated the differential expression of SIRT1 in normal human kidney cells and kidney cancer cell lines via experimental verification." (PMID 39845948, 2024).
lactic acidosis (1 paper, 2024). Metabolic acidosis characterized by the accumulation of lactate in the body. "Further support for our hypothesis of a disturbed NAD+/NADH ratios under lactic acidosis comes from altered mRNA expression of NAD+ consuming enzymes, such as phosphoglycerate dehydrogenase (PHGDH) and sirtuin-1 (SIRT-1)." (PMID 38195466, 2024).
laminopathy (1 paper, 2015). A rare genetic disorder caused by mutations in genes encoding proteins of the nuclear lamina. "Our recent work has further established the role of SIRT1 in delaying premature cellular senescence and aging by being involved in laminopathy-based premature aging." (PMID 25907989, 2015). "However, it remains to be seen whether SIRT1 also plays significant roles in delaying senescence or increasing lifespan in other models of laminopathy-based premature aging." (PMID 25907989, 2015).
language disorder (1 paper, 2024). A category of disorders characterized by an impairment in the development of an individual's language capabilities, which is in contrast to his/her non-verbal intellect. "To date, there have been few studies on the relationship between SIRT1 and language function, but in this study, the language disorder observed in patients with PD was mainly motor language disorder, which is driven by changes in the frontal lobe." (PMID 37718350, 2024).
learning disabilities (1 paper, 2024). "The results of this study are in line with other studies showing that SIRT-1 deficiency causes learning disabilities." (PMID 39061398, 2024).
leishmaniasis (1 paper, 2015). Infectious disease that is transmitted through the bite of hematophagous female phlebotomine sand flies. "Overall, our work demonstrates the importance of SIRT1 and AMPK energetic sensors for parasite intracellular survival and proliferation, highlighting the modulation of these proteins as potential therapeutic targets for the treatment of leishmaniasis." (PMID 25738568, 2015).
lymphopenia (1 paper, 2025). Reduction in the number of lymphocytes. "However, our results indicate that 3,4‐cPP is a functional agonist that activates S1P1 without internalization and suppresses the inflammatory response through the S1P1/SIRT1 pathway without inducing lymphopenia." (PMID 40470379, 2025).
mantle cell lymphoma (1 paper, 2019). Mantle cell lymphoma is a rare form of malignant non-Hodgkin lymphoma affecting B lymphocytes in the lymph nodes in a region called the ``mantle zone''. "Two alkylating agents, bendamustine and a metabolite of cyclophosphamide (4-hydroperoxy-cyclophosphamide, 4-OHCY) induce H3K18 acetylation and decrease the expression of SIRT1, SIRT7, and HDAC3 in a dose-dependent manner in mantle cell lymphoma (MCL) cells." (PMID 31121824, 2019).
metabolism (1 paper, 2019). "In this study we investigated whether SIRT1 is involved in the regulation of ZEA-induced lactate metabolism disorder in SCs." (PMID 31284444, 2019).
metastatic cancers (1 paper, 2014). A carcinoma which has spread from the original site of growth to another anatomic site. "SIRT1 inhibition could possibly be considered a target for treatment of metastatic cancers where both FZD7 and SIRT1 are overexpressed." (PMID 24897117, 2014).
metastatic melanoma (1 paper, 2018). A melanoma that has spread from its primary site to another anatomic site. "Therefore, SIRT1 may be a potentially valuable therapeutic target for metastatic melanoma." (PMID 29374154, 2018).
microphthalmia (1 paper, 2022). Congenital or developmental anomaly in which the eyeballs are abnormally small. "All Sirt1−/− mice in the BALB/c strain suffered some early development-related health issues including lower bodyweight and a microphthalmia-like condition for the entire life." (PMID 35484199, 2022).
mineral-bone disorders (1 paper, 2025). "Beyond its role in fibrosis, SIRT1 is also implicated in phosphate metabolism, vascular calcification, and mineral-bone disorders in CKD." (PMID 41009597, 2025).
Mitochondrial myopathy (1 paper, 2020). "A double-blind, randomized, placebo-controlled, cross-over trial of resveratrol (an activator of AMPK and SIRT1) in patients with mitochondrial myopathy has completed recently but the results have not been published." (PMID 33013660, 2020).